TNF (tumor necrosis factor)
Diseases named in the same sentence as TNF in open-access papers (continued):
Sharing a sentence is not in itself a finding about the gene and the disease.
bacteremia (122 papers, 1992 to 2025). "In the BP group, no serious infection or infusion-site reaction associated with anti-TNF-α antibody agents occurred although 1 patient manifested fever and infectious disease (i.e., transient bacteremia due to bacterial translocation)." (PMID 37083800, 2023). "For instance, it has been shown that fungal sepsis in neonates is associated with substantial increase in IL-6 and TNF-α levels, when compared with bacterial sepsis." (PMID 28367457, 2017). "In parallel with these data, the activation of the TLR4 signaling pathway, sensitivity to TLR4 inhibitors and production of TNFα are routinely associated with LPS-induced bacterial sepsis." (PMID 28542576, 2017). "Increased levels of IL-6, IL-8 and TNFα have been shown to be significantly increased in S. aureus patients compared to healthy controls and are associated with a complicated course of infection in S. aureus bacteremia patients." (PMID 36969151, 2023). "Moreover, MDR bacteremia was linked to higher levels of TNF-a, indicating a differential immune response." (PMID 37624004, 2023). "In summary, a high bacterial antigen load seems to be associated with the induction of IL-6 and TNF-α, and could cause an inflammatory cascade during bacteremia, potentially contributing to a detrimental outcome of invasive S. suis infection." (PMID 31947746, 2020). "Furthermore, a strong release of TNF-α and IL-6 into the blood was associated with bacteremia." (PMID 38675794, 2024). "Additionally, C. difficile damaged intestinal integrity as demonstrated by the increased serum FITC-dextran levels, causing gut leakage-induced bacteremia that enhanced the production of systemic inflammatory cytokines (serum IL-1β, TNF-α, KC, and MIP-2 levels as markers)." (PMID 34925261, 2021). "Monocytes/macrophages are cells of the monocytic lineage that are critical in bacterial sepsis, as they are the main source of inflammatory cytokines that are responsible for septic shock, such as tumor necrosis factor alpha (TNF-α), IL-1β, and IL-6." (PMID 40005560, 2025). "Estrogen can regulate the increase in Hp levels, while Hp maintains endotoxin tolerance by reducing TNFα levels (the main mediator of cytokine storm), thereby slowing the progression of bacterial sepsis." (PMID 40364840, 2025). "Estradiol administration prevents bacteremia following intraperitoneal inoculation of Enterococcus in ovariectomized rats by increasing TNF-α and NO levels." (PMID 40364840, 2025). "We used this concentration to mimic the physiological conditions of cytokine levels in the serum of patients with bacteremia, where the levels of IL-6 and IL-8 can reach several ng/ml and the level of TNFα can reach 1 ng/ml." (PMID 40540014, 2025). "A decrease in TNFα production after LPS challenge is a good indicator of bacteremia, as a decrease in TNFα production and in the number of circulating monocytes has been reported to correlate with bacteremia." (PMID 39559359, 2024). "There was significantly lower TNFα production after LPS challenge in patients with bacteremia than in HV (p = 1.1 × 10-6) or CS patients (p = 5.14 × 10-11)." (PMID 39559359, 2024). "A significant decrease in TNFα, IL-1β, and IL-8 production was observed in patients with documented bacteremia (p value < 0.05), and a significant increase in IL-10 was also detected (p value < 0.05)." (PMID 39559359, 2024). "To confirm low TNFα production after LPS challenge as a feature of bacteremia, we measured this response in a new ED cohort of patients whose blood cultures were positive within the first 24 hours of ED admission (n = 35)." (PMID 39559359, 2024). "In this study TNF peak concentrations were found when the bacteremia became undetectable (at 18 dpi) in both groups." (PMID 35925895, 2022).
bacteremia (continued). "In this study, we observed peak concentrations of IL-10 during bacteremia suggestive of an anti-inflammatory response dominated by IL-10, which likely links to low TNF production levels during bacteremia." (PMID 35925895, 2022). "Here, we show that septic JAM-A –/– mice have increased gut permeability, yet paradoxically have decreased bacteremia and systemic TNF and IL-1β expression." (PMID 35819838, 2022). "yoelii 17XNL, perhaps via degradation of TNF-α and promotion of a type-2 immune response that concordantly protects epithelial barrier integrity, while limiting the systemic response to bacteremia and parasite transmissibility." (PMID 35154114, 2022). "Peak serum levels of MIP-1a, MIP-β, G-CSF, VEGF, TNF, IL-2 and IL-12 (p40) were observed after the bacteremia was controlled for both groups." (PMID 35925895, 2022). "Recently, cytokine analysis demonstrated that interleukin (IL)-6, IL-10, and Tumor Necrosis Factor-α (TNF-α) were significantly elevated in pediatric hematology patients with G- bacteremia." (PMID 36544765, 2022). "Comparison of median cytokine levels between patients with true candidemia and patients with E. coli bacteremia showed significantly elevated TNF-α levels in bacteremic patients, whereas TGF-β levels were significantly elevated in IC (true) patients." (PMID 33535593, 2021). "In the bacterial sepsis group, TNF-alpha decreased over time, as examined by a generalized estimating equation (p=0·03); other inflammatory markers also decreased somewhat over time, though the differences were not statistically significant." (PMID 34956225, 2021). "In this context, E. coli bacteremia is reported to pathologically augment the production of TNF, an inflammatory cytokine that plays a key role in orchestrating the inflammatory cascade in CD57." (PMID 33594081, 2021). "On the other hand, treatments with the ER-β selective agonist, WAY-202196, exert a protective effect in both male and female rodents subjected to CLP by decreasing TNF-α and IL-6 levels, reducing bacteremia, and maintaining intestinal integrity." (PMID 29925409, 2018). "Continuous hemofiltration significantly decreases the serum levels of TBIL, DBIL, TBA, Lac, ammonia, TNF-α, IL-6, and improves 28-day mortality of patients with bacterial sepsis complicated by liver dysfunction." (PMID 30098593, 2018). "In particular, estradiol administration prevents bacteremia in ovariectomized rats intraperitoneally inoculated with Enterococcus faecalis by increasing TNF-α and NO levels." (PMID 29925409, 2018). "Targeting of TNF-α in animal models of bacterial sepsis led to a decrease of inflammatory mediators." (PMID 28442605, 2017). "It was found that the fungal sepsis is associated with substantial increase in all cytokines levels (TNF-α, IL-1β, IL-4, IL-6, and IL-10), when compared with bacterial sepsis." (PMID 28367457, 2017). "Although we were able to identify the CD14loCD16hi cells which have been described in bacterial sepsis, the proportion of these cells producing TNFα in response to stimulation with H37Rv and LPS was much less." (PMID 26567164, 2015). "In the present study, 3 cytokines (TNF-α, IL-1α, and KC) emerged as biomarkers for fatal outcome of S. aureus bacteremia." (PMID 23520553, 2013). "Proinflammatory responses induced in bacterial sepsis lead to dysregulated hemostasis and hypercoagulation, with a central role for TNF-induced expression of TF." (PMID 22347435, 2012). "The TNF-α-mediated morbidity or mortality in mouse models of cerebral malaria and bacterial sepsis also can be regulated by IFN-γ." (PMID 22911786, 2012). "Compared with controls, the levels of IL-6, IL-8, IL-9, IL-15, IL-17, IP-10 and TNFα were significantly elevated in the bacterial sepsis-ARDS group." (PMID 21062445, 2010).
bacteremia (continued). "FluA triggers a rapid activation of the innate immune pathways, such as NF-κB and STAT1/3, leading to an early and intense surge in proinflammatory cytokines, including TNF-α, IL-6, and IL-1β, that surpasses both the speed and magnitude of responses observed in bacterial sepsis." (PMID 41321454, 2025). "In bacteremia coinfections, one of the proinflammatory cytokines, such as TNF, was decreased." (PMID 36716305, 2023). "However, there was a pattern in 75% of patients that was distinct from bacterial sepsis: TNF-alpha and IL-6 production by circulating monocytes were sustained; furthermore, there were high levels of CRP, d-dimer and AST/ALT." (PMID 36289881, 2022). "His studies showed that TNF-alpha secreted by macrophages after LPS stimulation blocks the production of lipoprotien lipase and other enzymes necessary for fatty acid synthesis, which ultimately leads to the accumulation of lipoproteins during bacteremia." (PMID 33603020, 2021). "In addition, MDSC expansion and ex vivo production of IFN-gamma and TNF-alpha were resolving over time in bacterial sepsis, whereas in SARS-CoV-2, immunosuppression and inflammation were accelerating." (PMID 34956225, 2021). "In particular, ADAM17 was found to promote bacterial sepsis in mice by shedding of TNFα." (PMID 32825187, 2020). "Moreover, TNF-α levels were significantly higher in patients with persistent bacteremia than in those with short-term bacteremia (11.51 [4.51–15.65] vs 5.46 [3.18–8.91] pg/mL, p = 0.028)." (PMID 33256638, 2020). "The aim of the study was to evaluate the effects of continuous hemofiltration on 28-day mortality and the levels of total bilirubin (TBIL), direct bilirubin (DBIL), total bile acids (TBA), lactate (Lac), ammonia, TNF-α and IL-6 in patients with bacterial sepsis complicated by liver dysfunction." (PMID 30098593, 2018). "Interestingly, we also found a strong trend towards higher plasma TNF-α levels and the presence of bacteremia." (PMID 28475641, 2017). "As bacteremia is tightly linked with death, this is consistent with a previous study reporting increased TNF-α levels in non-survivors of melioidosis." (PMID 28475641, 2017). "Importantly, in the previous report and in our hands TNFα was barely secreted by the patient and in both cases this was accompanied by severe bacteremia." (PMID 26683521, 2015). "Moreover, the comparison of TNF-α concentrations in occurrence of bacteremia in relation to both fungemia (P = 0.614) and viremia (P = 0.884) was not significant." (PMID 26315105, 2015). "Finally, the absence of IL-1 decreases PGE2 in a model of M. tuberculosis-infected deficient mice, and the addition-of IL-1 or PGE2 reduces the bacteremia, whereas the TNF-induced LTB4 rises in wild-type animals." (PMID 26516315, 2015). "Blocking cytokines such as TNF- α, IL-6 and IL-1 did show benefit in patients with bacteremia." (PMID 21931850, 2011). "Furthermore, the limitations of the retrospective data precluded a comparison of the prognostic impact of PIV with other prognostic scores (e.g. the SOFA score or the Pitt bacteremia score...) or immune markers, including enzymes, immune cell subtypes, ILs, TNF-alpha, and CDs." (PMID 38789916, 2024). "In conclusion, 28-day mortality of patients with bacterial sepsis-associated liver dysfunction was significantly improved in the continuous hemofiltration group, which was related to the decreased serum levels of TBIL, DBIL, TBA, Lac, ammonia, TNF-α and IL-6 after 72 h treatment." (PMID 30098593, 2018). "However, whether the IL-1, IL-17, and TNF-α cytokines have a causative role in host survival and the cell types involved in these responses during S. aureus bacteremia is not entirely clear." (PMID 37483624, 2023). "The greatest increase in the synthesis of the pro-inflammatory cytokine TNF-α in response to LPS and LTA was observed in patients with BA, which can lead to an inadequate response to bacteremia." (PMID 36836906, 2023).
bacteremia (continued). "In contrast, patients with S. aureus bacteremia presented significantly elevated IL-10, IFN-γ, PTX3 and TNF-α levels compared to IC (other) patients." (PMID 33535593, 2021). "The ex vivo responsiveness of PBMCs to TLR4- and T cell-receptor activation, as measured by ELISpot quantification of both TNF-alpha and IFN-gamma respectively, differed between SARS-CoV-2 and bacterial sepsis patients." (PMID 34956225, 2021). "Not having explained variability in TNFα production in terms of monocyte surface markers with proven significance in bacterial sepsis, we next investigated the contribution of TLR signalling to TNFα response." (PMID 26567164, 2015). "In the bacterial sepsis-ARDS group, levels of IL-6, IL-8, IL-9, IL-15, IL-17, IP-10 and TNFα are also increased versus the control group." (PMID 21062445, 2010). "TNF-α showed poor diagnostic performance, with only an 18.1% positivity rate in bacteremia, though specific AUC values for TNF-α were not reported for Gram-negative cases." (PMID 40647525, 2025). "The inflammatory response seemed to vary between MDR and non-MDR bacteremia, regarding TNF-a, while no other significant differences in other cytokine levels were detected." (PMID 37624004, 2023). "The highest increase in the synthesis of pro-inflammatory cytokine TNF-α in response to LPS and LTA was observed in patients with BA, which could lead to an inadequate reaction to bacteremia." (PMID 36836906, 2023). "Taken together, we uncovered a role for IL-1R, but not IL-17A/F and TNF-α in protection against S. aureus bacteremia." (PMID 37483624, 2023). "Using a mouse model of S. aureus bacteremia, we demonstrated that IL-17A/F and TNF-α had no significant impact on survival, whereas IL-1R signaling was critical for survival during S. aureus bacteremia." (PMID 37483624, 2023). "Despite no bacteremia in all groups (data not shown), serum IL-1β, IL-6, and TNF-α (but not IL-10) were increased in the infected mice from both bacterial strains." (PMID 35955437, 2022). "Among all groups, only mice with SE > CT biofilms demonstrated mortality with the highest serum pro-inflammatory cytokines (TNF-α and IL-6), organ injury (kidneys and livers), and fungemia, but not bacteremia." (PMID 34746032, 2021). "Longitudinal analyses by LMM revealed that TNF-α, IL-6, and IL-10 concentrations were significantly increased in SAB patients who died within 30 d post-bacteremia (with SAB patients who survived as reference) (p = 0.001, p = 0.002, and p < 0.001, respectively)." (PMID 33256638, 2020). "Consistent with the literature, in this study, patients who died from SAB had significantly higher IL-6 and IL-10 levels during early-stage bacteremia, and patients who died within 7 days of SAB onset further displayed a significantly elevated IL-10/TNF-α ratio and TLR2 downregulation." (PMID 33256638, 2020). "In contrast, in sera from C57BL/6 mice exposed to MSHR5855, which did not exhibit appreciable bacteremia, we saw only a modest but significant increase in TNF-α, IL-2 and IP-10 but not until day 59 post-exposure." (PMID 30500862, 2018). "In our study, we found six of the soluble mediators analyzed that differentiated between patients with and without bacteremia: TNF-α, CCL4, TIMP-1, VCAM-1, ICAM-1, and E-selectin." (PMID 29681903, 2018). "According to the binary logistic regression analysis, TNF-α, IL-1α, KC, G-CSF, IL-6, IL-12p70, IP-10, and MIP-1α are indicative for presence of S. aureus bacteremia in mice, while TNF-α, IL-1α, and KC were also potential biomarkers for fatal outcome of this infection." (PMID 23520553, 2013). "A number of clinical trials with anti-inflammatory drugs, such as a monoclonal antibody against TNFα and an interleukin-1 receptor antagonist have been conducted to counteract the pathological inflammatory response in bacterial sepsis with little to no success." (PMID 38326335, 2024).
bacteremia (continued). "Bacterial sepsis induces systemic inflammation, which stimulates PCT production in almost all tissues released into the blood stream in response to bacterial endotoxins and inflammatory cytokines, such as tumor necrosis factor-alpha (TNF-α), interleukin-1-beta (IL-1β), and interleukin-6 (IL-6)." (PMID 39195007, 2024). "Similarly, heightened TNF-α production correlated with persistent rather than resolving bacteremia in patients." (PMID 37483624, 2023). "Another possibility for the lack of phenotype in TNF-α deficient mice is that lymphotoxin-α signals through the TNF-α receptors, which may have compensated for TNF-α deficiency in our S. aureus bacteremia model." (PMID 37483624, 2023). "With respect to TNF production, after the initial phase of primary innate immune activation resulting in increased production and enhanced chemotaxis, BCG appears to re-wire neonatal Mos for a tolerogenic response to subsequent stimulation, as occurs in bacterial sepsis." (PMID 34326836, 2021). "However, as measurement and evaluation of TNF-α and IL-1 kinetics were not part of the current study, further investigations are required to elucidate their role in TG synthesis during bacteremia." (PMID 30982158, 2019). "A high rate of bacteremia (60%) was observed in this study compared with 44% in a retrospective study assessing the natural history of TJA infections in RA patients not exposed to TNFα blockers." (PMID 20637100, 2010). "In addition, as the study was retrospective did not include specific prognostic scores (SOFA score, Pitt bacteremia score or others...) and immune markers such as enzymes, immune cell subtypes, ILs, TNF-alpha, CDs, we could not compare PIV with other specific markers." (PMID 38789916, 2024). "The authors found that, during the first week, leukocytes have a reduced ability to produce IL-2 (interleukin-2), TNF-α (tumor necrosis factor-α) and IFN-γ (interferon-γ) in response to a non-self in patients with bacterial sepsis." (PMID 36982221, 2023). "However, other studies have shown conflicted findings in the serum level of IL-2, which were not significantly different in candidemia compared to bacteremia, whereas serum levels of IL-8, IFN-γ and TNF-α were non-significantly increased." (PMID 34684298, 2021). "IL-6 and IL-10 levels were significantly higher in non-survivors than in survivors on days 2–5 post-bacteremia (P = 0.010 and P = 0.021, respectively), and those dying within 7 d of SAB (n = 3) displayed significantly higher IL-10/TNF-α ratios than the survivors did (P = 0.007)." (PMID 33256638, 2020). "Using unsupervised hierarchical clustering, we found that TNFα, CCL4, E-selectin, VCAM-1, ICAM-1, and TIMP-1 could be used to discriminate between patients with and those without bacteremia." (PMID 29681903, 2018). "In addition, the patients with bacteremia also showed a trend toward higher levels of TNF-α in plasma (median 3.65, IQR 0–7.28) compared with those with no bacteremia (median 0.53, IQR 0–4.51, P = 0.06)." (PMID 28475641, 2017). "We believe that differences in TNF‐α and IL‐1β plasma levels could not be detected in the COVID‐19 groups, in comparison with the healthy individuals, because the cytokine storm is milder in SARS‐CoV‐2 infections than in bacterial sepsis, being more difficult to detect." (PMID 38328863, 2024).